CGAS (cyclic GMP-AMP synthase)
Diseases named in the same sentence as CGAS in open-access papers (continued):
Sharing a sentence is not in itself a finding about the gene and the disease.
tumor (continued). "Relative to other signaling pathways, the TGF-β/SMAD and cGAS–STING pathways have been the subject of more in-depth discussions due to their dual roles in the process of tumor metastasis." (PMID 39090094, 2024). "The endogenous stimulation of cGAS-STING pathway in cancer can occur through uptake of tumor cell derived DNA, which will be abundant in hypoxic and necrotic zones, conditions that promote DNA damage and nuclear leaks." (PMID 38389103, 2024). "The DNA exonuclease TREX1 plays a critical role in regulating the immune balance of cGAS signaling and acts as an upstream modulator of radiation-induced anti-tumor immunity." (PMID 39736508, 2024). "Collectively, our data suggest that PRMT3-mediated methylation of HSP60 at R446 prevents the activation of anti-tumor immunity through the maintenance of mitochondrial integrity and inhibition of cGAS/ STING activation HCC in vitro and in vivo." (PMID 39256398, 2024). "Our study does show DNA methyltransferase inhibitors such as zebularine can potentiate anti-tumor immunity by inducing tumor immunogenicity and improving antigen processing through cGAS-STING pathway." (PMID 38755254, 2024). "We presented the mechanism of GSDME in anti-tumor immunity through activating cGAS-STING-IFNβ axis mediated by mitochondrial damage, leading to more infiltration of CD8+T cells with synergistic efficacy with ICIs." (PMID 38853246, 2024). "The role of cGAS in tumors has been extensively studied, revealing its dual function in both promoting and inhibiting tumor progression." (PMID 40018367, 2024). "In APCs, particularly in tumor-resident DCs, the activation of the cGAS-STING pathway lays the basis for the activation and proliferation of T cells, leading to the infiltration of CD8+ T cells and the initiation of immune responses against tumors." (PMID 38999073, 2024). "IR-induced DNA damage leads to cytosolic dsDNA accumulation in tumor cells, activating the cGAS (cyclic GMP-AMP synthase)-STING (stimulator of interferon genes) pathway." (PMID 38792088, 2024). "The cyclic GMP–AMP synthase (cGAS)–stimulator of interferon genes (STING) pathway has been recognized as a key regulator of the tumor-immune microenvironment in various cancer types, including GC11,12." (PMID 39242811, 2024). "Another line of research focused on the cGAS-STING pathway in tumor cells characterized by chromosomal instability (CIN)." (PMID 38523155, 2024). "Here, we demonstrated that tumor cell-intrinsic cGAS–STING was highly expressed in dMMR GC compared to pMMR/EBV (−) GC." (PMID 39242811, 2024). "Murine models also revealed important role of NK cells in the anti-tumor activity following cGAS-STING pathway activation." (PMID 38832958, 2024). "By enhancing MOMP-induced inflammation through caspase inhibition, we and others have shown that engaging CICD in tumour cells can lead to anti-tumour immunity dependent on cGAS-STING and NF-κB signalling in the dying cell." (PMID 38337057, 2024). "Depletion of TREX1 contributes to the derepression of tumor-intrinsic innate immune response by accelerating the accumulation of cytosolic dsDNA derived from DNA damage and leading to a cGAS-STING pathway activation." (PMID 39177280, 2024). "It has also been demonstrated that dying cancer cells release dsDNA that can be taken up by phagocytic cells in the tumor, leading to cGAS/STING activation." (PMID 38659582, 2024). "Similar cGAS-STING scores have been used to investigate the correlation with tumor immune microenvironment features." (PMID 38167507, 2024). "Therapies that disrupt DNA damage repair to elevate cytosolic DNA levels synergize with anti-tumor immunotherapy by activating the cGAS pathway." (PMID 39201539, 2024). "In the study described herein, we reveal a new mechanism by which tumor exosomal ENPP1 can hydrolyze 2′3′‐cGAMP effectively to inhibit cGAS‐STING pathway activation in immune cells." (PMID 38498770, 2024).
tumor (continued). "Collectively, based on the results of our extensive in vitro experiments, tumor exosomal ENPP1 definitely plays a crucial role in the regulation of cGAS‐STING signaling pathway." (PMID 38498770, 2024). "Tumor cells crosstalk with MSCs through an intercellular cGAS‐cGAMP‐STING signaling loop, leading to increased production of interferon‐β (IFNβ) by MSCs." (PMID 38638003, 2024). "They not only caused DNA damage but also inhibited its repair, leading to the leakage of DNA fragments into the cytoplasm to activate the cGAS-STING pathway in tumor and immune cells." (PMID 38999073, 2024). "In contrast, STING overexpression in cGAS cells (cGAS (+)/STING (+)) had little effect on tumor growth and vascular normalization compared with cGAS (+)/STING (−) cells." (PMID 38177099, 2024). "Activation of cGAS induces the production of type I interferons (IFNs), which initiate innate immune responses against tumor cells." (PMID 38782895, 2024). "The accumulation of DNA resultant from radiotherapy or chemotherapy can activate the cGAS/STING pathway in DCs and tumor-associated macrophages (TAMs), modulating IFN-gamma levels in DCs and thereby facilitating CD8 infiltration." (PMID 38785789, 2024). "While THT led to innate immune cell stimulations highlighted by gene expression upregulation in the STING cGAS pathway and enhanced M1 and dendritic cell levels, tumor regrowth was observed within six days post-treatment." (PMID 39872527, 2024). "Apart from its intrinsic function in tumor and immune cells, cGAS-STING can signal intercellularly by cGAMP spreading to neighboring cells via gap junctions." (PMID 38660307, 2024). "Within the APCs, these tumor-derived DNA fragments can be sensed by cGAS, which then activates the STING pathway." (PMID 38347787, 2024). "As a summary of this research, we proposed that active RSK2 phosphorylates cGAS at Ser120 and Thr130 by tumor promoters, such as EGF and bFGF." (PMID 39424777, 2024). "We further assessed the roles of host STING in tumor cGAS-mediated vascular normalization and anti-tumor immune response." (PMID 38177099, 2024). "Cytoplasmic double-stranded DNA from microbial infection (bacterial DNA, viral DNA or reverse transcribed viral RNA), mitochondria, tumour cells or dead cells binds to and activates cyclic GMP-AMP synthase (cGAS) 1, which starts a signalling cascade reaction." (PMID 38164186, 2024). "Altogether, these observations indicated that the combination of Olaparib and XL413 inhibits tumor growth and exerts anti‐tumor immunity through cGAS‐STING‐type I interferon pathway and potentiating the function CD8+ T cells in OV." (PMID 39412086, 2024). "Tumor-derived DNA is capable of escaping from phagolysosomes into the cytosol, where it is recognized by cGAS, thereby activating the cGAS-STING signaling pathway." (PMID 39379603, 2024). "In adenocarcinoma, STING activation by cGAMP induced IL12 expression in tumor tissues and IL-12 levels in response to DNA were reduced in STING- or cGAS-deficient dendritic cells." (PMID 38389103, 2024). "In terms of mechanism, CKIP‐1 silencing induced TFAM downregulation disrupted mitochondrial homeostasis to activate the tumour‐suppressing cGAS‐STING axis in OSCC cells." (PMID 39169452, 2024). "Cytosolic double-stranded DNA from either pathogen-derived or tumor sources binds and activates cytosolic cGAS to generate the host cyclic dinucleotide (CDN) second messenger cyclic GMP-AMP (cGAMP)." (PMID 38095464, 2024). "Radiation-induced DNA damage can activate the cGAS-STING pathway and induce T-cell responses, and the combination of radiotherapy with STING agonists causes a more potent anti-tumor effect." (PMID 38347787, 2024). "Meanwhile, in GI cancers, cGAS-mediated pathways have been shown to be both oncogenic and tumor suppressive." (PMID 39050748, 2024). "Prior work has demonstrated that tumor‐specific cGAS can trigger STING signaling in NK cells via cGAMP transfer." (PMID 39206412, 2024).
tumor (continued). "cGAS can also promote tumor progression through both STING-dependent and STING-independent mechanisms." (PMID 40018367, 2024). "dsDNA released by the tumor cells can also be taken up by dendritic cells, resulting in cGAS activation." (PMID 38659582, 2024). "In MC38 colon tumors and human squamous cell carcinoma, recruitment of regulatory T cells and mobilization of myeloid-derived suppressor cells by the cGAS-STING pathway leads to reduced tumor immunogenicity." (PMID 40018367, 2024). "Adequate activation of the cGAS-STING pathway and expression of M1-associated genes in macrophages are central to efficacious anti-tumor immunity, but they are compromised in the presence of miR-25/93 that can be imported by EVs released by hypoxic GBM cells." (PMID 38389103, 2024). "Tumor-derived DNA can lead to the activation of cGAS, resulting in cellular senescence, initiation of pro-inflammatory cascades, and IFN-1 signaling-mediated innate immune responses." (PMID 39050748, 2024). "The targeted activation of cGAS and subsequent enhancement of anti-tumor immunity by nanocomposites highlight their substantial potential in cancer treatment." (PMID 39050748, 2024). "They work by damaging DNA in tumor cells, leading to the production of DNA fragments and activation of the cGAS-STING pathway." (PMID 38999073, 2024). "The cGAS-STING pathway is involved in activating or inhibiting the anti-tumor immune response, with the intensity and timing of cGAS-STING pathway activation as well as the type and state of the tumor." (PMID 38693472, 2024). "Activation of innate immune pathways within tumor cells, such as the cGAS-STING and RIG-I-MAVS signaling pathways, is essential to achieve this goal and improve overall anti-tumor immunity." (PMID 40018367, 2024). "Activated cGAS-STING pathway in tumor cells lead to upregulation of various inflammatory genes, such as Type I interferon and impedes the neoplastic progression." (PMID 38510490, 2024). "As a result, JIB‐04 not only activated the tumour‐intrinsic cyclic GMP‐AMP synthase (cGAS)‐STING pathway via DNA‐damage‐induced cytosolic DNA accumulation, but also promoted ICD, releasing numerous damage‐associated molecular patterns." (PMID 38390756, 2024). "Here, we will elucidate the roles and distinctions of IFN-I treatment and cGAS-STING pathway activation in the tumor immune cycle." (PMID 38512518, 2024). "Further modification with the RS17 peptide for tumor targeting enabled a combination of photodynamic therapy, ferroptosis, and cGAS-STING pathway activation, resulting in enhanced antitumor efficacy through a synergistic effect." (PMID 39033108, 2024). "Accretive evidence for the cGAS/STING-mediated anti-tumour immunity has emerged for multiple malignancies including PDAC." (PMID 39372406, 2024). "The activation of cGAS-STING pathway by tumor-derived dsDNA has tremendous potential to improve antitumor immunity, playing an essential role in DC recognition of dying tumor cells, by generating I-IFN response and potently enhanced antitumor CTL responses." (PMID 39020402, 2024). "Cdc2‐like kinase 1 (CLK1) promotes residual tumor cell survival, and CLK1 suppression enhances the sensitivity to cGAS inhibitors by decreasing proliferation‐associated nascent RNAs." (PMID 38145335, 2024). "These drugs function by binding to NLRC3, effectively inhibiting its negative regulatory function and unleashing the anti-tumor potential of the cGAS-STING pathway." (PMID 39439455, 2024). "These functions of the cGAS-STING pathway are crucial mechanisms for inducing tumor cell death and also form the basis for our understanding of the role the cGAS-STING pathway plays in tumors." (PMID 38523155, 2024). "The cGAS-STING pathway is an essential innate immune signal that plays a crucial role in the anti-tumor immune response." (PMID 39691393, 2024).
tumor (continued). "We assessed the tumor‐killing activity of cGAS‐STING pathway inhibitors because high cGAS/STING expression was correlated with poor outcomes in patients with PTCL." (PMID 38145335, 2024). "Activation of cGAS-STING signaling pathway with STING agonists results in anti-tumor immune response mediated by innate immunity stimulation." (PMID 38832958, 2024). "In this study, OMVs were collected and biomineralized by manganese oxide (MnO2), obtaining OM@MnO2-PEG nanoparticles for enhanced radio-immunotherapy of tumor via increasing the RT-caused ICD and cGAS-STING activation." (PMID 38831378, 2024). "The generation of type I interferons by the stimulation of the cGAS-STING pathway has the potential to significantly enhance anti-tumor immunity." (PMID 38370484, 2024). "The involvement of the cGAS‐STING pathway in the RECQL4‐mediated tumor‐promoting immune blockade was tested in vivo." (PMID 38381090, 2024). "DNA damage induced by radiation exposure can lead to micronuclei formation and trigger cGAS-mediated innate immune response in tumor cells in various environments, including those with ERCC1 or BRCA1/2 deficiencies." (PMID 39420203, 2024). "The tumor cell-intrinsic cyclic GMP–AMP synthase (cGAS)–stimulator of interferon genes (STING) pathway has been considered a key regulator of immune cell activation in the TME." (PMID 39242811, 2024). "The tumor cell-intrinsic expression of cGAS–STING was significantly higher in dMMR and EBV (+) GCs compared to pMMR/EBV (−) GC." (PMID 39242811, 2024). "A plethora of studies have shown that conventional therapies, including chemo and therapeutic radiation, promote cytosolic tumor DNA accumulation and cGAS/STING-mediated type I IFN antitumor immune responses." (PMID 38912586, 2024). "This would influence the interaction between paracrine tumor cells and bystander immune cells by inhibiting cGAS‐STING signaling pathway." (PMID 38498770, 2024). "The effectiveness of the radiation-induced anti-tumor immune response is terminated when cGAS activation signaling is halted." (PMID 38347787, 2024). "The therapeutic potential of robust cGAS-STING pathway activation in GBM has been demonstrated by use of synthetic cGAMP as a STING agonist that promotes anti-tumor immunity, implicating both T cells and innate immune cells such as macrophages." (PMID 38389103, 2024). "Studies have shown that cytoplasmic dsDNA produced by tumour cells can be delivered to macrophages, activate the cGAS–STING pathway, activate T cells and increase the sensitivity of these cells to ICIs." (PMID 39592436, 2024). "With increased exosome concentration, tumor‐derived exosomes exhibited positive regulation of cGAS‐STING signaling due to enhanced assistance of exosomes to 2′3′‐cGAMP." (PMID 38498770, 2024). "On the other hand, reactivation of cGAS expression enhances immune activity, facilitating the recognition and clearance of tumor cells and thereby increasing overall treatment efficacy." (PMID 38782895, 2024). "Encouraged by the superior induction of STING signaling initiated by cGAS EVs in vitro, we then determined the therapeutic potential in tumor models." (PMID 38518087, 2024). "Our findings thus reveal an overlooked tumor‐promoting effect of MSCs in the TME by increasing the expression of NK inhibitory ligands in CTCs via an intercellular cGAS‐STING‐IFNβ‐HLA signaling loop, which helps CTCs evade NK cell surveillance in the blood." (PMID 38638003, 2024). "These tumor‐derived exosomes also exhibited dual regulation in the cGAS‐STING pathway by both assisting 2′3′‐cGAMP to enhance STING signaling and hydrolyzing 2′3′‐cGAMP through ENPP1 to inhibit STING signaling." (PMID 38498770, 2024). "cGAS and STING have been shown to be silenced in several cancer types, suggesting a potential antitumor role for tumor-intrinsic cGAS/STING signaling." (PMID 39621308, 2024).
tumor (continued). "In tumor models, NLRC3 knockout mice display enhanced anti-tumor immune responses, suggesting that NLRC3 contributes to tumor immune evasion by regulating the cGAS-STING pathway." (PMID 39439455, 2024). "A key point for improving the efficacy of immunotherapy is the stimulation of innate immunity, and cGAS-STING signalling has for years been considered a therapeutic target to contribute to anti-tumour immunity." (PMID 39215193, 2024). "While defects in MMR reduced in vivo tumor growth in comparison to wild-type tumor cells, concomitant deletion of tumor cGAS, STING, or IFNAR1 rescued these growth defects, indicating a key role of cGAS/STING-type I IFN axis in immune surveillance." (PMID 39544936, 2024). "Beyond high-contrast in vivo hypoxic tumor imaging, the hypoxia-triggered PTT/PDT attributes elicited by the probe jointly activated ICD and the cGAS-STING pathway to enhance tumor-specific immune response and mitigate immunological resistance." (PMID 39613774, 2024). "As a critical component of intracellular DNA recognition, the cGAS-STING pathway primarily modulates tumor immune functions by eliciting the expression of IFN-I." (PMID 38512518, 2024). "cGAS, combined with dsDNA from dying tumor cells, catalyzes the production of the second messenger cyclic GMP-AMP synthase (cGAMP)." (PMID 39736508, 2024). "Targeting PRMT3-dependent HSP60 methylation disrupts mitochondrial integrity and increases mitochondrial DNA (mtDNA) leakage, which results in cGAS/STING-mediated anti-tumor immunity." (PMID 39256398, 2024). "Further studies have shown that cGAS/STING signaling can promote tumor cell survival in an autocrine and paracrine manner." (PMID 39544936, 2024). "On the other hand, emerging evidence suggested a pro-tumor role of the cGAS-STING pathway, which makes the clinical administration of STING agonists more challenging." (PMID 39020402, 2024). "Studies have shown that cGAS-STING agonists not only induce tumor cell senescence but also boost adaptive anticancer immunity and combine efforts with immunotherapy." (PMID 39737190, 2024). "Spatial immunological changes including augmented lymphoid infiltration into the tumor epithelium and locally increased cGAS/STING1 and type I IFN gene expression were observed in radiation-indomethacin–treated 4T1 tumors." (PMID 38912586, 2024). "This can occur from cGAMP produced by cGAS directly in dendritic cells or via cGAMP secreted from tumor cells." (PMID 38659582, 2024). "Radiation promotes CD8+T cells infiltration by inducing DSBs to activate the cGAS-STING pathway and enhances anti-tumor immune responses by releasing tumor-associated antigens and chemokines." (PMID 38431575, 2024). "cGAMP formed after the activation of cGAS in tumor cells can be taken up by non-tumor cells in the TME, activating the STING pathway." (PMID 38523155, 2024). "Mn2+ is also engaged in the innate immune detection of tumors, as Mn-insufficient mice had significantly enhanced tumor growth and metastasis and greatly reduced tumor-infiltrating CD8+ T cells in a cGAS-STING-dependent manner." (PMID 38612580, 2024). "As a multifunctional signaling axis, cGAS-STING-IFN-I participates in nearly all stages of the tumor immune cycle, playing a pivotal role in the tumorigenesis process." (PMID 38512518, 2024). "As a recognized cytosolic DNA sensor that activates anti-tumor immunity, cGAS has been less studied in its relationship with HPV proteins compared to IRF3 or STING." (PMID 39156107, 2024). "The synergistic combination of PDT, ferroptosis, and cGAS-STING pathway activation led to enhanced tumor treatment effects." (PMID 39033108, 2024).